SDHAP3 (SDHA pseudogene 3)
Synonyms: formerly SDHAL; SDHACL
Gene: Transcribed unprocessed pseudogene on chromosome 5 (1,572,222 to 1,593,289, reverse strand). Ensembl gene ENSG00000185986.
Diseases named in the same sentence as SDHAP3 in open-access papers:
SDHAP3 is named in the same sentence as 5 diseases in open-access papers, as found by Europe PMC text mining. Sharing a sentence is not in itself a finding about the gene and the disease. The quoted sentences say what the papers report.
developmental delay (1 paper, 2017). "Genes such as GNA15 and SDHAP3 that contained maternal smoking-associated DMRs displayed a developmental delay in mRNA up-regulation in smoking exposed." (PMID 28149327, 2017). "Gene expression analysis of SYCE3 revealed low gene expression in early second-trimester smoking exposed (p value = 0.02), analogous to the SDHAP3 mRNA results indicative of developmental delay in smoking exposed." (PMID 28149327, 2017).
tumor (2 papers, 2022 to 2024). "The composite plot indicated that SDHAP1, SDHAP3, DDX12P, CLUHP3, and RRN3P3 demonstrated high expressions in the low-risk subtype, which were categorized as tumor-suppressor pseudogenes in our study." (PMID 36438489, 2022). "We identified some mutation markers specific to tumor types, including some typical tumor‐related genes (e.g., TP63, ABCC1, ABCC5, and TFDP1 in ESCA) as well as numerous noncoding genes (e.g., NPSR1‐AS1 and AC079466.1 in HCC) and pseudogenes (e.g., SDHAP3 and TPTEP1 in LUAD)." (PMID 38010945, 2024). "Compared to HPV negative, patients with HPV positive had significantly higher expressions of oncogene pseudogenes (SDHAP1, SDHAP3, DDX12P, CLUHP3, and RRN3P3), but there was no prominent difference in the expressions of tumor-suppressor pseudogenes (PDIA3P1, LDHAP4, LDHAP7, EEF1A1P6, and EEF1A1P11)." (PMID 36438489, 2022).
cancer (1 paper, 2022). A tumor composed of atypical neoplastic, often pleomorphic cells that invade other tissues. "SDHAP3 plays an important role in carcinogenesis in our study, which also displays strong involvement in neurodevelopmental disorders, and cancer susceptibility." (PMID 36438489, 2022).
SDHAP3 also shares sentences with these, for which no sentence is quoted: cardiovascular disease (1 paper); neurodevelopmental disorder (1).